STIL (STIL centriolar assembly protein)
Diseases named in the same sentence as STIL in open-access papers (continued):
Sharing a sentence is not in itself a finding about the gene and the disease.
bladder cancer (6 papers, 2022 to 2025). "To further disclose the potential mechanism behind STIL-driven malignant behaviors in bladder cancer, we analyzed the differentially expressed genes in STIL-deficient UMUC3 cells and wild-type UMUC3 cells." (PMID 36497260, 2022). "PC-related protein—SCL/TAL1 interrupting locus (STIL) is a differential expression gene that we screened from bladder cancer and adjacent normal tissues." (PMID 37101292, 2023). "The purpose of our study was to investigate the role of STIL in bladder cancer (BC) tumorigenesis for the first time." (PMID 36497260, 2022). "In several cancers with bad prognosis, STIL expression has been found up-regulation, including lung cancer, prostate adenocarcinoma, bladder cancer, and ovarian cancers." (PMID 35155425, 2022). "On these RNA-seq data, we found that STIL mRNA expression was significantly up-regulated in BBN-induced bladder cancer tissues, compared with control samples." (PMID 36497260, 2022). "Our previous study also revealed that STIL was up-regulated, and the positive percentage of primary cilia is reduced in bladder cancer." (PMID 35155425, 2022). "To further verify the expression levels of STIL in bladder cancer (BC), we analyzed the RNA-seq datasets of several BC tissues from TCGA." (PMID 36497260, 2022). "Using public databases; we observed that STIL is highly expressed in bladder cancer and is closely related to the cell cycle." (PMID 36497260, 2022). "In urinary bladder cancer, STIL contributes to cell proliferation by inhibiting primary cilia formation through its interaction with AURKA, while in triple-negative breast cancer, it promotes malignancy by activating the Fanconi anemia pathway through KLF16 interactions." (PMID 39727708, 2024). "STIL silencing induces PC assembly, prevents G0/G1 phase cells transfer to the G2/M phase, inhibits SHH signalling and causes cell proliferation and growth inhibition in bladder cancer cells." (PMID 37101292, 2023). "This study found that STIL expression was up-regulated in bladder cancer tissues and cell lines." (PMID 37101292, 2023). "We speculated that PC deficiency due to STIL overexpression could inhibit the activated form of SMO and induce the activated form of GLI1 to promote tumorigenesis in bladder cancer." (PMID 37101292, 2023). "Our results suggest that STIL may be a promising potential therapeutic target for bladder cancer." (PMID 36497260, 2022). "In contrast to silencing individual genes, co-silencing in STIL and AURKA produces more encouraging results in bladder cancer cells." (PMID 37101292, 2023). "RNA-seq results and immunoblotting experiments confirmed that STIL enhanced the PI3K/AKT/mTOR pathway, resulting in increased c-myc expression which ultimately promoted the occurrence and progression of bladder cancer." (PMID 36497260, 2022). "Similarly, STIL has been reported to decrease c-Myc expression via the PI3K/AKT/mTOR pathway, thereby inhibiting bladder cancer cell proliferation." (PMID 40961099, 2025). "Furthermore, AURKA depletion could reverse the malignancy phenotype, PC disassembly, and SHH signalling activation induced by STIL overexpression in BLCA cells, suggesting that STIL regulation for PC is dependent on AUKRA in bladder cancer." (PMID 37101292, 2023). "Currently; there are no reports on the role of STIL in bladder cancer." (PMID 36497260, 2022).
lymph node metastasis (5 papers, 2017 to 2025). "Key prognostic factors included tumor size >5cm, lymph node metastasis, sTIL levels, estrogen receptor (ER) status and pCR." (PMID 38420013, 2024). "A decline in sTIL levels was also seen in cases with lymph node metastasis, implying that inadequate immune infiltration may facilitate dissemination." (PMID 41367471, 2025). "In ILC, increasing sTIL levels are associated with a poor OS and a decreased DFS independent of lymph node metastases and ILC molecular subtypes, as determined in a multivariate analysis." (PMID 37296857, 2023).
Primary microcephaly (5 papers, 2011 to 2024). Head circumference below 2 standard deviations below the mean for age and gender at birth. "STIL mutations associated with resistance to proteasomal degradation and centrosome amplification are a cause of primary microcephaly." (PMID 39466849, 2024). "In line, germline truncating STIL mutations that lead to centrosome amplification cause primary microcephaly in humans." (PMID 39466849, 2024). "Genes associated with primary microcephaly were often differentially expressed during development, with highest expression during the early embryonic and fetal periods (ASPM, WDR62, MCPH1, STIL, KIF23 and TTI1)." (PMID 32182809, 2020).
gastric cancer (4 papers, 2019 to 2022). A primary or metastatic malignant neoplasm involving the stomach. "There has been a recent report suggesting STIL-mediated regulation of AKT protein in gastric cancer and another one suggesting AKT-mediated regulation of β-catenin in CRC." (PMID 34485108, 2021). "A previous study also indicated that STIL knockdown suppresses the progression of gastric cancers." (PMID 35155425, 2022). "A recent study has delineated that STIL regulates PI3K/AKT in gastric cancer." (PMID 34485108, 2021). "However, the role and mechanism of STIL in gastric cancer (GC) remain elusive." (PMID 31187582, 2019).
ovarian carcinoma (4 papers, 2017 to 2022). A malignant neoplasm originating from the surface ovarian epithelium. "Ovarian cancer was excluded because the samples were small and STIL only mutated in two of these samples." (PMID 35155425, 2022). "STIL depletion has been shown to enhance DNA double-strand breaks caused by DNA damaging agents in ovarian cancer." (PMID 34485108, 2021). "We show here that depletion of STIL in ovarian cancer cells caused chromosomal aneuploidy and the formation of micronuclei that might have caused the increased sensitivity to DNA damage." (PMID 28423708, 2017). "Hedgehog signaling has been reported to regulate expression of ABC transporters in ovarian epithelial cancer, and STIL, being a positive regulator of GLI1-mediated hedgehog regulation, was found to be significantly regulating side population in CRC cells." (PMID 34485108, 2021). "Ovarian cancer cells were more sensitive to the depletion of STIL than to other centriolar replication factors including PLK4, SASS6 and CENPJ." (PMID 28423708, 2017). "Here we report that an unbiased shRNA screen identified STIL as essential for ovarian cancer cell survival." (PMID 28423708, 2017). "The therapeutic cooperation between STIL siRNA and cisplatin observed in the preclinical cancer models raised the possibility that STIL depletion enhances the sensitivity of ovarian cancer cells to DNA damaging agents." (PMID 28423708, 2017). "Analysis of published TCGA data revealed that STIL is ubiquitously expressed in ovarian cancer and that its mRNA levels significantly correlate with a more advanced histological grade." (PMID 28423708, 2017). "We therefore examined the effect of STIL depletion on chromosomal aneuploidy in ovarian cancer cells two days after transfection with siRNA against STIL." (PMID 28423708, 2017). "ShRNA screen performed in 42 ovarian cancer cell lines identified the centriolar replication factor STIL as an essential gene for ovarian cancer cells." (PMID 28423708, 2017). "However, in a recent study, STIL repression was shown to have a synergistic effect with DNA-damaging agents in ovarian cancer." (PMID 34485108, 2021). "Here, we report that STIL, a protein expressed in advanced ovarian cancer, may be such a novel therapeutic target." (PMID 28423708, 2017). "We observed that STIL was essential for growth in 10 of the 42 ovarian cancer cell lines tested." (PMID 28423708, 2017). "Thus, STIL knockdown sensitizes ovarian cancer cells to DNA damaging chemotherapy." (PMID 28423708, 2017). "Indeed, knockdown of STIL significantly enhanced the sensitivity to cisplatin in HeyA8, IGROV1 and RMG1 ovarian cancer cells reducing the IC50 from a mean of 19μM (range: 13.3-30μM) to 6μM (range: 3.3-10μM; P<0.01 two tailed T-test)." (PMID 28423708, 2017).
prostate carcinoma (4 papers, 2021 to 2023). A carcinoma that arises from epithelial cells of the prostate gland. "We first focus on STIL, which has been found to influence cell cycle progression by regulating the PC in kidney and prostate cancer in our previous study." (PMID 37101292, 2023). "Finally, we validated that STIL participated in the primary cilia formation and regulated cell cycle progression in prostate cancer and kidney cancer cell lines, revealing that STIL played a critical role in regulating cancer cells through primary cilia." (PMID 35155425, 2022). "STIL could regulate PC and affect the cell cycle of kidney and prostate cancer cells." (PMID 37101292, 2023). "SCL-interrupting locus protein (STIL), previously identified in prostate cancer, is a G2 phase gene involved in cell growth and development." (PMID 35948941, 2022).
T-cell acute lymphoblastic leukemia (4 papers, 2013 to 2024). Acute lymphoblastic leukemia of T-cell origin. "STIL, also known as SIL, was initially identified at a genomic rearrangement site in a patient with T-cell acute lymphoblastic leukemia and has been implicated in the regulation of centrosome integrity and mitotic spindle organization." (PMID 39727708, 2024). "The STIL Centriolar Assembly Protein (STIL) was first discovered as a deleted locus in T-cell acute lymphoblastic leukemia." (PMID 36899391, 2023). "STIL also known as SIL, was originally identified at the site of a genomic rearrangement in a T-cell acute lymphoblastic leukemia patient, which has been implicated in regulating centrosome integrity and mitotic spindle organization." (PMID 35365182, 2022). "A chromosomal translocation involving the STIL gene is reported in T-cell acute lymphoblastic leukemia (T-ALL)." (PMID 23472065, 2013).
colon carcinoma (3 papers, 2018 to 2022). "STIL knockout showed different blockade phases in different tumor types, and reduced the proliferation of cervical and colon cancer cells by inhibiting Cyclin B1/CDK1, which, in turn, induced cell cycle arrest in the G2/M phase." (PMID 36497260, 2022). "To assess the role of STIL enrichment in colon cancer with disease prognosis, we used c-Bioportal cancer database." (PMID 34485108, 2021).
colorectal cancer (3 papers, 2021 to 2025). A primary or metastatic malignant neoplasm that affects the colon or rectum. "For instance, through the transduction of Wnt and Shh signals, STIL promotes colorectal cancer cell growth and stemness." (PMID 39718123, 2025). "For example, STIL promotes colorectal cancer cell proliferation and tumor growth by enhancing Shhh and Wnt signaling pathways and stimulates stemness in tumor cells." (PMID 39718123, 2025). "In this study, we have explored the role of STIL gene in tumorigenesis and studied its molecular targets in colorectal cancer (CRC)." (PMID 34485108, 2021). "In contrast, high STIL expression patients showed a better prognosis in colorectal cancer." (PMID 35155425, 2022). "Furthermore, high expression of STIL in colorectal cancer has been observed." (PMID 39718123, 2025).
lung adenocarcinoma (3 papers, 2022 to 2025). A carcinoma that arises from the lung and is characterized by the presence of malignant glandular epithelial cells. "TCGA data revealed upregulated STIL mRNA expression in lung adenocarcinoma (LUAD) and lung squamous cell carcinoma (LUSC), the two major subtypes of NSCLC." (PMID 39727708, 2024). "To investigate SCL/TAL 1 interrupting locus (STIL)’s role and prognostic significance in lung adenocarcinoma (LUAD) progression, we examined STIL and E2 promoter binding factor 1 (E2F1) expression and their impacts on LUAD prognosis using Gene Expression Profiling Interactive Analysis (GEPIA)." (PMID 39735672, 2025). "The human lung adenocarcinoma cell lines, CL1-3 and CL1-5, which are derived from the parental CL1-0 and possess progressive migration and invasiveness capabilities, were used to examine the oncogenic role of STIL." (PMID 35365182, 2022).
osteosarcoma (3 papers, 2021 to 2026). A usually aggressive malignant bone-forming mesenchymal neoplasm, predominantly affecting adolescents and young adults. "Highly expressed STIL was associated with the ability to distinguish osteosarcoma from non-osteosarcoma samples, and the patients with high STIL expression are associated with a poor prognosis." (PMID 33858425, 2021). "STIL is associated with osteosarcoma proliferation and invasion, and may be promote the progression of osteosarcoma by regulating the expression of CDK1, CCNB2, CDC20, CCNA2, BUB1 and AURKB." (PMID 33858425, 2021). "Therefore, this study sought to elucidate the biological function of STIL in osteosarcoma and the underlying molecular mechanism." (PMID 33858425, 2021). "Second, the biological functions of STIL in osteosarcoma were investigated using proliferation, apoptosis, migration and invasion experiments." (PMID 33858425, 2021). "After silencing STIL, osteosarcoma cell proliferation decreased, apoptosis increased, and the migratory and invasion ability decreased." (PMID 33858425, 2021). "SCL/TAL1 interrupting locus (STIL) is associated with the progression of several tumors; however, the biological role of STIL in osteosarcoma remains poorly understood." (PMID 33858425, 2021). "STIL expression in 376 osteosarcoma samples was higher than that in 92 normal samples, and the total SMD integrated by the random effects model was 1.52 (95 % confidence interval [CI] 0.98–2.05)." (PMID 33858425, 2021). "STIL expression was silenced in osteosarcoma cell lines to observe the effects on proliferation, apoptosis, invasion, and migration." (PMID 33858425, 2021). "In this study, STIL was found to play a role of a proto-oncogene in osteosarcoma and was significantly involved in the occurrence and development of osteosarcoma." (PMID 33858425, 2021). "The Transwell assay results revealed that osteosarcoma cell migration was significantly inhibited after STIL was silenced." (PMID 33858425, 2021). "This is the first study to report the overexpression of STIL in osteosarcoma, and demonstrate that silencing STIL inhibits cell proliferation, promotes cell apoptosis, and suppresses invasion and migration capabilities." (PMID 33858425, 2021). "In the PPI network, we selected six genes (CDK1, CCNB2, CDC20, CCNA2, BUB1, and AURKB) as the core STIL differentially co-expressed genes in osteosarcoma." (PMID 33858425, 2021). "In general, we confirmed that STIL plays a role as a proto-oncogene, is highly expressed in osteosarcoma, and is involved in osteosarcoma proliferation and invasion." (PMID 33858425, 2021). "The potential molecular mechanism of STIL in osteosarcoma was further explored by Gene Ontology (GO) and Kyoto Encyclopedia of Genes and Genomes (KEGG) pathways." (PMID 33858425, 2021). "Of the osteoblast cell lines and four osteosarcoma cell lines, it was found that the up-regulation of STIL mRNA was the most significant in the U-2 OS and HOS cell lines." (PMID 33858425, 2021). "To study the expression of STIL in osteosarcoma cells, we detected the level of STIL mRNA by qRT-PCR." (PMID 33858425, 2021). "In this study, 13 gene chips were collected and it was found that STIL expression was significantly increased in osteosarcoma." (PMID 33858425, 2021). "Silencing STIL can decrease the malignant progression of osteosarcoma cells and increase apoptosis." (PMID 39718123, 2025). "Despite these findings, the clinical significance and biological function of STIL in osteosarcoma remains unknown." (PMID 33858425, 2021). "Of particular interest is whether STIL is also highly expressed in osteosarcoma, and whether it promotes the progression of osteosarcoma as observed in other cancers." (PMID 33858425, 2021). "In addition, the apoptosis experiments revealed that compared with the control group, there was an increase in the level of apoptotic osteosarcoma cells after knocking down STIL, which was statistically significant in U-2 OS cells, but not in HOS cells." (PMID 33858425, 2021).
osteosarcoma (continued). "A CCK8 assay was used to observe the effect of STIL on osteosarcoma cell proliferation, and the results revealed that a knockdown of STIL could significantly inhibit the proliferation of osteosarcoma cells." (PMID 33858425, 2021). "In addition, to study the effect of STIL on osteosarcoma cells, we inhibited STIL expression in the two cell lines with the highest expression levels (U-2 OS and HOS)." (PMID 33858425, 2021). "As an important factor in the process of mitosis, STIL may participate in the progression of osteosarcoma by regulating the cell cycle." (PMID 33858425, 2021). "Moreover, the bioinformatics analysis showed that STIL may participate in the biological function of osteosarcoma by regulating CDK1, CCNB2, CDC20, CCNA2, BUB1, and AURKB." (PMID 33858425, 2021). "Additionally, the in vitro experiments revealed that the silencing of STIL could significantly block proliferation, induce apoptosis, and reduce migration and invasion in osteosarcoma cells." (PMID 33858425, 2021). "To further clarify the potential molecular mechanism of STIL in osteosarcoma, we performed a GO and KEGG enrichment analysis on the STIL differentially co-expressed genes, and they were found to be significantly enriched in the cell cycle pathway." (PMID 33858425, 2021).
triple-negative breast carcinoma (3 papers, 2020 to 2024). An invasive breast carcinoma which is negative for expression of estrogen receptor (ER), progesterone receptor (PR), and human epidermal growth factor receptor 2 (HER2). "Our results are in line with previous analyses suggesting an association between high sTIL scores and prognosis among patients with triple-negative breast cancer." (PMID 32408905, 2020).
hepatocellular carcinoma (2 papers, 2023 to 2024). A malignant tumor that arises from hepatocytes. "Additionally, in hepatocellular carcinoma, STIL expression has been linked to immune cell infiltration and immune checkpoint expression and has been proposed as a predictive marker for immunotherapy and chemotherapy efficacy." (PMID 39727708, 2024). "However, the role of STIL in the biological mechanism of hepatocellular carcinoma (HCC) remains unclear." (PMID 36899391, 2023).
lymphoma (2 papers, 2014 to 2024). A malignant (clonal) proliferation of B- lymphocytes or T- lymphocytes which involves the lymph nodes, bone marrow and/or extranodal sites. "Compared to healthy lymph nodes, STIL protein expression was increased in lymphomas from both B6-STIL control and CMV-STIL-transgenic mice irrespective of their genotype." (PMID 39466849, 2024). "STIL mRNA levels gradually increased in lymphomas derived from B6-STIL control, CMV-STIL+/- and CMV-STIL+/+ mice and were higher than the respective levels in healthy lymph nodes from B6-STIL control, CMV-STIL+/- and CMV-STIL+/+ animals." (PMID 39466849, 2024).
mental disorder (2 papers, 2015 to 2016). A disease that has its basis in the disruption of mental process. "More than 80 proteins were identified in neuron projection term, and these proteins may influence metabolic process or cellular process in mental disorders, such as STIL (SCL/TAL1 interrupting locus) and XPO1 (exportin 1)." (PMID 27917343, 2016).
pancreatic cancer (2 papers, 2020 to 2024). "βPix/COOL-1 has also been shown to interact with PAK1 (p21-activated kinase) and STIL (SCL/TAL1-interrupting locus), to promote actin remodelling and promote cancer cell migration in pancreatic cancer models suggesting a potential mechanism for the βPix/COOL-1 mediated invasion evident in GBM." (PMID 33256106, 2020).